OR10J5 (olfactory receptor family 10 subfamily J member 5)
Description:
Olfactory receptor. Activated by the synthetic floral odorant, lyral, and by alpha-cedrene, a sesquiterpene constituent of cedarwood oil. Its activation increases intracellular Ca(2+). Acts as a key regulator of myogenesis through its actions on cell migration and adhesion by activating the Ca(2+)-dependent AKT signal transduction pathway (By similarity). Also acts as a regulator of angiogenesis. Moreover, plays a role in the regulation of lipid accumulation in hepatocytes via the cAMP-PKA pathway. May be involved in sperm chemotaxis and motility (By similarity).
Synonyms: MOR23; OLFR16; OR1-28
Tractability: Antibody: UniProt places it where antibodies can reach, with high confidence; its Gene Ontology location is reachable by antibodies, with high confidence; UniProt predicts a signal peptide or a membrane-spanning region.
Gene: Protein-coding gene on chromosome 1 (159,535,078 to 159,536,007, reverse strand). Ensembl gene ENSG00000184155.
Subcellular location: Cell membrane
Pathways (Reactome):
Sensory Perception: Expression and translocation of olfactory receptors; Olfactory Signaling Pathway
Gene Ontology:
Molecular function: olfactory receptor activity; G protein-coupled receptor activity
Biological process: G protein-coupled receptor signaling pathway, coupled to cyclic nucleotide second messenger; lipid homeostasis; regulation of angiogenesis; sensory perception of smell; chemotaxis; detection of chemical stimulus involved in sensory perception of smell; regulation of muscle cell differentiation; G protein-coupled receptor signaling pathway
Cellular component: plasma membrane; membrane
Genetic constraint (gnomAD): Loss-of-function variants: 2 observed, 0.52 expected, observed/expected ratio (o/e) 3.81. That is too few expected variants to judge how well the gene tolerates losing a copy. Missense variants: 387 observed, 389.89 expected, observed/expected ratio (o/e) 0.99, 90% interval 0.91 to 1.08. Synonymous variants: 170 observed, 144.33 expected, observed/expected ratio (o/e) 1.18, 90% interval 1.04 to 1.34.
Homologues: Orthologues: chimpanzee OR10J5 (98% identical), mouse Or10j5 (87% identical), pig OR10J5 (87% identical), rat Or10j5 (87% identical), dog OR10J5 (86% identical), rabbit OR10J5 (84% identical). Paralogues in human: OR10J1 (72% identical), OR10J3 (59% identical), OR10T2 (51% identical), OR10Z1 (51% identical), OR10K2 (50% identical), OR10R2 (49% identical), OR10K1 (48% identical), OR1J4 (44% identical), OR10J4 (42% identical), OR2A1 (42% identical), OR2A12 (42% identical), OR2A42 (42% identical), and 116 more.
Diseases named in the same sentence as OR10J5 in open-access papers:
OR10J5 is named in the same sentence as 6 diseases in open-access papers, as found by Europe PMC text mining. Sharing a sentence is not in itself a finding about the gene and the disease. The quoted sentences say what the papers report.
Hepatic steatosis (2 papers, 2017 to 2024). Steatosis is a term used to denote lipid accumulation within hepatocytes. "Inspired by a previous study that reported knockdown of OR10J5 (a human ortholog of MOR23) leading to increased lipid accumulation in hepatocytes, we aimed to investigate the potential role of MOR23 in hepatic steatosis." (PMID 39417398, 2024). "Here, using MOR23- and OR10J5-expressing Hana3A cells, we identified α-cedrene, a natural compound that protects against hepatic steatosis in mice fed the high-fat diet, as a novel agonist of these receptors." (PMID 28842679, 2017).
aneurysm (1 paper, 2024). Bulging or ballooning in an area of an artery secondary to arterial wall weakening. "Among other receptors identified with functions relevant to the cardiovascular system, OR10J5 (Olfr16) has been found in human aortic samples; it would thus be useful to further evaluate its role with regard to aneurysm development." (PMID 39768700, 2024).
OR10J5 also shares sentences with these, for which no sentence is quoted: Glucose intolerance (2 papers); muscular dystrophy (1); nonalcoholic fatty liver disease (1); Obesity (1).